CD33 (CD33 molecule)
Diseases named in the same sentence as CD33 in open-access papers (continued):
Sharing a sentence is not in itself a finding about the gene and the disease.
MALT lymphoma (1 paper, 2019). An indolent, extranodal type of non-Hodgkin lymphoma composed of small B-lymphocytes (centrocyte-like cells). "Furthermore, the CD33+CD11b+ MDSCs were also enriched in the gastric MALT lymphoma biopsies, which correlated with significant upregulation of Arg-1 and iNOS compared to paired normal gastric tissues." (PMID 32063899, 2019).
mesenchymal neoplasms (1 paper, 2025). "The diffuse expression of CD45, CD33, CD43, and BCL-2 in our case was instrumental in confirming the myeloid origin and ruling out other hematolymphoid or mesenchymal neoplasms." (PMID 41234969, 2025).
morbid obesity (1 paper, 2023). An excess of body weight, normally defined as an individual with a body mass index greater than 35 or a body weight greater than one hundred percent of ideal body weight. "Compared to cluster 2, cluster 1 showed higher CD183, CD11b, and CD33 expression and was significantly increased in patients with morbid obesity compared to the CTRL." (PMID 37266430, 2023).
Onset (1 paper, 2022). The age group in which disease manifestations appear. "Several independent GWASs have also identified CD33 as a strong genetic locus linked to late-onset AD (LOAD), where rs3865444 and rs12459419 were the most commonly studied SNPs." (PMID 36192375, 2022).
oropharyngeal cancer (1 paper, 2015). Carcinoma, predominantly squamous cell, arising from the epithelial cells of the oropharynx. "Flow cytometry results showed that CD11b+ LIN- HLA-DR- CD33+ MDSCs was obviously up-regulated in the specimens of HPV 16 infection with dysplasia, caner in situ and oropharyngeal cancer in comparsion with normal oral mucous." (PMID 26193368, 2015).
osteomyelitis (1 paper, 2024). An acute or chronic inflammation of the bone and its structures due to infection with pyogenic bacteria. "By contrast, reduced frequencies of CD33 + HLA-DR + monocytes and CD11b expression on myeloid cells linked to lower osteomyelitis risk suggest that constraining the activation and adhesive capacity of these innate populations could alleviate damage due to inflammation." (PMID 38650858, 2024).
osteonecrosis (1 paper, 2025). A none disease characterized by death of bone tissue due to a lack of blood supply. "However, research on CD33− HLA DR + Myeloid cell in osteonecrosis remains limited." (PMID 41194914, 2025). "Furthermore, the results of mediation analysis demonstrated that the absolute count of CD33− HLA DR + Myeloid cell and T cell %lymphocyte mediated the protective effect of the superpathway of sulfate assimilation and cysteine biosynthesis of the gut microbiota on osteonecrosis." (PMID 41194914, 2025).
ovarian tumor (1 paper, 2018). "Flow cytometry revealed that 85.1% of CD33+ cells were confined to the CD33+CD11b+LIN− HLA-DR−/low type in ovarian tumor samples, and these cells expressed high levels of Arginase 1 regardless of HLA-DR expression." (PMID 29703902, 2018). "Using immunostaining, we evaluated the expression of CD33, a marker of human MDSCs, in primary ovarian tumors and in peritoneal disseminations." (PMID 29703902, 2018).
Pancytopenia (1 paper, 2023). An abnormal reduction in numbers of all blood cell types (red blood cells, white blood cells, and platelets). "Preliminary clinical evaluation of anti-CD33 CAR T cells in patients with AML indeed showed on-target/off-tumor toxicity to HSPCs and myeloid progenitors, observed as pancytopenia after treatment." (PMID 37583386, 2023).
Pleural effusion (1 paper, 2022). The presence of an excessive amount of fluid in the pleural cavity. "Flow cytometry of pleural effusion showed about 87.8% of myeloid blasts, and their immunophenotypes were positive for CD34, CD117, CD33, and CD56, and partially positive for HLA-DR and CD11b." (PMID 36281103, 2022).
polymyositis (1 paper, 2024). A rare idiopathic inflammatory myopathy characterized by symmetric proximal muscle weakness and elevated muscle enzymes. "Specifically, polymyositis demonstrated the capacity to decrease the levels of 2 immune cell types (OR < 1, P < .05): B cell panel: CD28 on secreting CD4 regulatory T cell and myeloid cell panel: CD45 on CD33‐ HLA-DR‐." (PMID 39470507, 2024).
psoriasis (1 paper, 2020). An autoimmune condition characterized by red, well-delineated plaques with silvery scales that are usually on the extensor surfaces and scalp. "We found that the accumulation of human MDSCs (CD11b+ CD33+ HLA-DR−) is remarkably increased in psoriatic skin lesions compared with healthy controls, indicating there is a correlation between psoriasis and the accumulation of MDSCs, to some extent." (PMID 32684837, 2020).
pulmonary TB (1 paper, 2015). "CD14 analysis was not performed in the pulmonary TB patients, even if a heterogeneous morphology (granulocytic and monocytic) was described by light microscopy on HLA-DR-/CD33+ isolated cells." (PMID 25879532, 2015).
rectal cancer (1 paper, 2020). A primary or metastatic malignant neoplasm that affects the rectum. "In the present study, we evaluated the clinical relevance of circulating and intratumoral CD33+CD11b+HLA-DR− MDSCs in patient with locally advanced rectal cancer undergoing neoadjuvant chemo-radiotherapy." (PMID 32903466, 2020). "To conclude, here we show, for the first time, that intratumoral, but not circulating CD33+HLA-DR−CD16−CD11b+ MDSCs bare suppressive capabilities and are associated with decreased rate of pathological response to nCRT in patients with locally advanced rectal cancer." (PMID 32903466, 2020).
respiratory failure (1 paper, 2022). The significant impairment of gas exchange within the lungs resulting in hypoxia, hypercarbia, or both, to the extent that organ tissue perfusion is severely compromised. "Moreover, CD33 and circulating IL-6 levels were higher among patients with severe respiratory failure, i.e., PaO2/FiO2 ratio of <13.3 kPa." (PMID 35625671, 2022).
Senile plaques (1 paper, 2024). Senile plaques are extracellular deposits of amyloid in the gray matter of the brain. "Different polymorphisms of CD33 are thought to influence the AD pathological process by affecting microglial activation, interfering with microglial-mediated Aβ clearance, and promoting the accumulation of senile plaques." (PMID 38241287, 2024).
spondyloarthropathy (1 paper, 2005). A group of inflammatory rheumatic diseases associated with arthritis and enthesitis, and often involving the axial skeleton. "We have previously shown that synovial tissue in RA and spondyloarthropathy is enriched in differentiated myeloid DCs that express CD33, CD11c, MHC class II, costimulatory molecules, and nuclear RelB." (PMID 15743469, 2005).
Stroke (1 paper, 2022). Sudden impairment of blood flow to a part of the brain due to occlusion or rupture of an artery to the brain. "Considering that UC is less aggressive and has less frequent extra-intestinal manifestations than CD33, the lower inflammatory burden of UC than that in CD could be a possible explanation for the lack of association between UC and stroke." (PMID 35798796, 2022).
synucleinopathies (1 paper, 2024). "Beyond known PD genes GBA1 and LRRK2, rare variants AD genes (CD33, CR1 and PSEN2) and Aβ toxicity modifiers involved in RhoA/actin cytoskeleton regulation (ARGHEF1, ARHGEF28, MICAL3, PASK, PKN2, PSEN2) were shared risk factors across synucleinopathies." (PMID 38496508, 2024).
tuberculosis (1 paper, 2016). A chronic, recurrent infection caused by the bacterium Mycobacterium tuberculosis. "The ROS production and the profile of surface molecule expression (with the exception of CD33), suggest that LDGs in tuberculosis are activated neutrophils that have degranulated." (PMID 27073889, 2016). "With the exception of the expression of CD33, all these phenotypic characteristics of LDGs derived from in vitro challenge with Mtb are consistent with those of LDGs in patients with tuberculosis." (PMID 27073889, 2016).
uveitis (1 paper, 2018). An inflammatory process affecting a part of or the entire uvea. "Accordingly, in this study, elevated frequencies of granulocytic CD11b+ CD14− CD15+ CD33+ (MDSC) were found in IAU patients during uveitis activity and might be linked to the increased presence of Th17 cells." (PMID 30105034, 2018).
viral hepatitis (1 paper, 2025). An acute or chronic inflammation of the liver parenchyma caused by viruses. "To elucidate the mechanisms underlying the cognitive function differences conferred by CD33 SNPs among individuals with viral hepatitis, we examined the interactions between these SNPs and inflammation severity." (PMID 40637125, 2025). "Moreover, these insights present promising avenues for therapeutic strategies, advocating the targeted modulation of CD33 in addressing neurocognitive disorders associated with chronic viral hepatitis or sustained inflammation." (PMID 40637125, 2025). "To summarise, our moderation analysis highlights the specific enhancement of the effect of CD33 SNPs, namely rs12985029 and rs3826656, on cognitive functions in the context of viral hepatitis." (PMID 40637125, 2025). "Among the six cognitive functions assessed – executive function, visuospatial function, memory, psychomotor speed, attention and language – the influence of CD33 SNPs was most evident in the memory domain among individuals with chronic viral hepatitis." (PMID 40637125, 2025). "This study highlights the importance of CD33 SNPs in cognitive outcomes, emphasising their role in the context of chronic viral hepatitis." (PMID 40637125, 2025). "Second, the observed interactions between CD33 and chronic viral hepatitis underscoring the profound moderating effect of chronic inflammation on CD33 functions." (PMID 40637125, 2025). "A significant effect of rs3826656 on delayed recall of logical memory was found solely within the HCV cohort (q = 0.001) in moderation analysis, providing additional evidence of the enhanced effect of CD33 SNPs on cognitive performance in the context of viral hepatitis." (PMID 40637125, 2025). "We also excluded participants with psychiatric disorders, to minimise factors that could confound the relationship between viral hepatitis, CD33 SNPs and cognition." (PMID 40637125, 2025). "Furthermore, the systemic inflammation induced by chronic viral hepatitis moderates the CD33 SNP effect." (PMID 40637125, 2025). "The significant effect of CD33 SNPs on delayed recall of logical memory was also exclusively observed within the HBV (q = 0.023) and HCV (q = 0.023) groups, reinforcing the substantial role of CD33 SNPs among viral hepatitis patients." (PMID 40637125, 2025). "Taken together, these findings clarify the interactions between CD33 and chronic HBV and HCV in determining cognitive trajectories, and provide promising therapeutic avenues to combat neurocognitive dysfunctions arising from chronic viral hepatitis or broader neurodegenerative challenges." (PMID 40637125, 2025).
tumor (397 papers, 2010 to 2026). "Whereas CD33 CARs killed both MV-4-11 variant lines equally, CD33 | CD16b Tmod cells exhibited over 100x-fold increased killing of tumor cells compared to surrogate normal." (PMID 40191207, 2025). "Despite the relative appeal of CD33 as an AML tumor-associated antigen (TAA), therapeutics targeting CD33 have substantial clinical toxicity, presumably caused at least in part by expression on healthy myeloid cells." (PMID 40191207, 2025). "The evolution of ADC target selection has progressed from hematologic-specific CD antigens (e.g., CD30, CD22, CD33, CD79b) to tumor-associated antigens more commonly expressed in solid tumors, such as HER2, TROP2, Nectin-4, and folate receptor α." (PMID 41184856, 2025). "In human HCC, M-MDSCs are enriched in the fibrotic livers surrounding the tumor area, and the expression of M-MDSC marker CD33 is positively associated with tumor progression and negatively associated with the survival rate of HCC patients." (PMID 38397901, 2024). "Tumor hypoxia and infiltration by Tregs and also by CD33+ MDSCs are independent risk factors in GBM." (PMID 34681642, 2021). "In a tumor challenge test, mice immunized with the DNA vaccine, encoding HSP70 linked with HPV16 mE7 and the human CD33 peptide gene, remained tumor-free for approximately two months, in contrast to unimmunized mice, which developed tumors within two weeks." (PMID 34960608, 2021). "Tumor-associated lineage−CD45+CD33+ MDSCs from high-grade ovarian serous cancer patients suppress proliferation of T cells and inhibit their function through downregulating the expression of IL-2, INF-γ, and granzyme B, resulting in increased tumor volume." (PMID 34359674, 2021). "As expected, anti-CD33 CAR-T cells caused an on-target/off-tumor effect because CD33 is also expressed on myeloid progenitors." (PMID 33567640, 2021). "The levels of METTL3 and CD33+ MDSCs in tumour tissues were notably associated with reduced DFS or OS." (PMID 33059689, 2020). "We observed increased levels of METTL3 and CD33+ MDSCs in tumour tissues and positive associations between the levels of METTL3 and CD33+ MDSCs." (PMID 33059689, 2020). "Further, increased GM-CSF was associated with higher T stage, and CD33+S100a9+ cell infiltration was associated with higher tumour grade and less differentiated tumours." (PMID 32747748, 2020). "Lo Russo revealed that M2-like CD163+ CD33+ PD-L1+ tumor-associated macrophages can block anti-PD-1 antibody functional activity by interacting with the Fc domain of the antibody." (PMID 32727409, 2020). "CD33 is expressed on myeloid progenitors and CD33-targeted CAR T therapy was reported to cause an on-target off-tumor effect which compromised hematopoiesis." (PMID 32019116, 2020). "The high levels of METTL3 and CD33+ MDSCs in the CC tumour microenvironment were significantly associated with poor disease-free survival (DFS) and overall survival (OS) in CC patients." (PMID 33059689, 2020). "In oral squamous cell carcinoma, VISTA expression correlated with MDSC markers (CD11b and CD33) and was associated with increased expression of IL13Rα2, an important cytokine involved in tumor metastasis and recruitment of MDSCs20." (PMID 32873829, 2020). "Zhang and colleagues described that high levels of tumor-infiltrating CD33+ cells were associated with an advanced disease stage and poor OS (p < 0.01, n = 116)." (PMID 32967190, 2020). "We found that tumor-infiltrating CD33+ MDSCs were significantly associated with shorter overall survival (OS) and a reduced disease-free interval." (PMID 31001284, 2019). "Gemtuzumab ozogamicin is a conjugated monoclonal antibody against CD33 and linked to a cytostatic agent, calicheamicin, an anti-tumor antibiotic." (PMID 26237023, 2015). "The change in Treg observed within the tumor showed an inverse relationship with clinical benefit and greater decrease in tumor MDSC subset Lin1−/HLA-DR−/CD33+/CD11b+ was associated with improved PFS at one year." (PMID 24498358, 2014).
tumor (continued). "Greater decrease in tumor MDSC Lin1−/HLA-DR−/CD33+/CD11b+ was associated with improved PFS at one year (p = 0.04)." (PMID 24498358, 2014). "A higher density of CD33+/p-STAT1+ cells within tumor nests was associated with a lower density of CD8+ T cells (Spearman’s rho = −0.538, p < 0.001)." (PMID 23307253, 2013). "Furthermore, the dual tumor-associated antigen targeting improves therapeutic specificity by preferentially eliminating CD117+CD33+ cells, possibly allowing improved bispecific antibody-mediated AML therapy." (PMID 41911066, 2026). "Here, we characterized the pre-clinical anti-tumor activity of CC-96191 using a variety of shorter-term in vitro assays to define the principles underlying the drug’s cytolytic effects, and contrasted the results to those obtained with a potent CD33/CD3 BsAb." (PMID 38473239, 2024). "Due to the consumption of GO in the peripheral blood and poor ability to enter the bone marrow, high levels of CD33 tumor burden in the peripheral blood and high levels of circulating CD33 confer resistance to the medication and are linked with weaker responses." (PMID 38255313, 2024). "However, relapse was most consistently associated with mixed chimerism in the CD33+ fraction of bone marrow samples, reflecting the myeloid origin of the tumor cells." (PMID 35210563, 2022). "In addition, we found that high levels of METTL3 in tumour cells (HR: 5.502, P = 0.001) and in tumour-infiltrating immune cells (HR: 6.021, P = 0.001) and a high density of CD33+ MDSCs (HR: 5.755, P = 0.001) were associated with decreased OS." (PMID 33059689, 2020). "Increased tumor CD33+ myeloid cells were associated with better prognosis in the current study." (PMID 32150594, 2020). "The results indicate that METTL3 could directly induce CD33+CD11b + HLA-DR− MDSC differentiation or tumour-associated MDSC differentiation in vitro." (PMID 33059689, 2020). "Other possible mechanisms underlying HPD could be linked to tumor-infiltration by M2-like CD163+CD33+PD-L1+ clustered epithelioid macrophages or to specific gene expression signatures." (PMID 36046388, 2020). "Several AML tumour-associated antigens are at the forefront of targeted therapy development, which include CD33, CD123, CD13, CLL-1 and CD38 and which may be present on both AML blasts and leukemic stem cells." (PMID 31434267, 2019). "Therefore, if CAR33 treatment is used as a bridge to transplant, the toxicity associated with CD33 on-target off-tumor killing will be time-limited." (PMID 30524966, 2018). "However CD33 is expressed on normal cells of myeloid lineage and the reported anti-tumor effects were associated with profound cytopenias." (PMID 27367478, 2016). "The expression of inhibitory CD33-related Siglecs, including human Siglec-7 and Siglec-9 and murine Siglec-E, on tumor-associated macrophages (TAMs) was shown to support cancer progression by driving macrophage polarization toward the tumor-promoting M2 phenotype." (PMID 36322632, 2022). "Importantly, we demonstrated that knockdown of METTL3 in CD33+ cells or HeLa cells could attenuate MDSC or tumour-associated MDSC differentiation in vitro." (PMID 33059689, 2020). "To locally interfere with the CD47-SIRPα axis at the tumor site, we generated the so-called local inhibitory checkpoint monoclonal antibodies (licMABs), which consist of the endogenous SIRPα V-like domain linked to a mAb targeting CD33, a validated target antigen in AML." (PMID 28061465, 2017). "CARs used in AML often targeted CD123 and CD33; development of more diverse targets, including cell signaling of tumor growth (FLT3, NKG2D, TIM3, FRβ), addressed heterogeneity." (PMID 42109662, 2026). "Typical ADC drugs such as Gemtuzumab Ozogamicin utilize an anti-CD33 monoclonal antibody to precisely deliver the DNA-damaging molecule calicheamicin into tumor cells." (PMID 40843358, 2025).